ARC (activity regulated cytoskeleton associated protein)
Description:
Master regulator of synaptic plasticity that self-assembles into virion-like capsids that encapsulate RNAs and mediate intercellular RNA transfer in the nervous system. ARC protein is released from neurons in extracellular vesicles that mediate the transfer of ARC mRNA into new target cells, where ARC mRNA can undergo activity-dependent translation. ARC capsids are endocytosed and are able to transfer ARC mRNA into the cytoplasm of neurons. Acts as a key regulator of synaptic plasticity: required for protein synthesis-dependent forms of long-term potentiation (LTP) and depression (LTD) and for the formation of long-term memory. Regulates synaptic plasticity by promoting endocytosis of AMPA receptors (AMPARs) in response to synaptic activity: this endocytic pathway maintains levels of surface AMPARs in response to chronic changes in neuronal activity through synaptic scaling, thereby contributing to neuronal homeostasis. Acts as a postsynaptic mediator of activity-dependent synapse elimination in the developing cerebellum by mediating elimination of surplus climbing fiber synapses. Accumulates at weaker synapses, probably to prevent their undesired enhancement. This suggests that ARC-containing virion-like capsids may be required to eliminate synaptic material. Required to transduce experience into long-lasting changes in visual cortex plasticity and for long-term memory (By similarity). Involved in postsynaptic trafficking and processing of amyloid-beta A4 (APP) via interaction with PSEN1 (By similarity). In addition to its role in synapses, also involved in the regulation of the immune system: specifically expressed in skin-migratory dendritic cells and regulates fast dendritic cell migration, thereby regulating T-cell activation (By similarity).
Synonyms: hArc; Arg3.1; KIAA0278
Tractability: Antibody: its Gene Ontology location is reachable by antibodies, with high confidence; UniProt places it where antibodies can reach, with medium confidence. PROTAC: UniProt records ubiquitination sites on it; ubiquitination databases record sites on it.
Gene: Protein-coding gene on chromosome 8 (142,611,049 to 142,614,479, reverse strand). Ensembl gene ENSG00000198576.
Subcellular location: Extracellular vesicle membrane; Postsynaptic cell membrane; Synapse; Postsynaptic density; Early endosome membrane; Cell projection, dendrite; Cytoplasm, cytoskeleton; Cytoplasm, cell cortex; Cell projection, dendritic spine; Cytoplasmic vesicle, secretory vesicle, acrosome; Cytoplasmic vesicle, clathrin- coated vesicle membrane
Subcellular location (Human Protein Atlas): Microtubules; Vesicles
Pathways (Reactome):
Signal Transduction: NGF-stimulated transcription
Gene Ontology:
Molecular function: mRNA binding; protein binding; structural molecule activity
Biological process: dendritic spine morphogenesis; long-term memory; long-term synaptic potentiation; modulation of chemical synaptic transmission; mRNA transport; protein homooligomerization; regulation of dendritic spine morphogenesis; regulation of long-term synaptic depression; regulation of long-term synaptic potentiation; regulation of neuronal synaptic plasticity; vesicle-mediated intercellular transport; regulation of postsynaptic neurotransmitter receptor internalization
Cellular component: cytoplasm; plasma membrane; virus-like capsid; cytosol; dendritic spine; early endosome membrane; extracellular vesicle; membrane raft; neuronal cell body; neuronal ribonucleoprotein granule; postsynaptic density; postsynaptic membrane; synapse; acrosomal vesicle; cell cortex; clathrin-coated vesicle membrane; cytoskeleton; dendrite; glutamatergic synapse
Genetic constraint (gnomAD): Loss-of-function variants: 10 observed, 12.15 expected, observed/expected ratio (o/e) 0.82, 90% interval 0.51 to 1.39. The synonymous counts are far from expectation, so gnomAD's model fits this gene poorly and the ratio says little. Missense variants: 323 observed, 339.34 expected, observed/expected ratio (o/e) 0.95, 90% interval 0.87 to 1.04. Synonymous variants: 188 observed, 150.37 expected, observed/expected ratio (o/e) 1.25, 90% interval 1.11 to 1.41.
Homologues: Orthologues: chimpanzee ARC (99% identical), macaque ARC (97% identical), guinea pig ARC (95% identical), dog ARC (94% identical), mouse Arc (93% identical), rat Arc (93% identical), pig ARC (92% identical), tropical clawed frog arc (41% identical).
Diseases named in the same sentence as ARC in open-access papers:
ARC is named in the same sentence as 59 diseases in open-access papers, as found by Europe PMC text mining. Sharing a sentence is not in itself a finding about the gene and the disease. The quoted sentences say what the papers report.
schizophrenia (16 papers, 2014 to 2024). A major psychotic disorder characterized by abnormalities in the perception or expression of reality. "Mammalian ARC is required for synaptic plasticity and long term memory, and mutations in human Arc are associated with neuronal disorders like schizophrenia, Alzheimer’s, and autism spectrum disorders." (PMID 38089935, 2023). "Nonetheless, the transcriptomic and proteomic profiles presented here for ARC-KO HEK293 cells contribute to our understanding of the mechanisms underlying the effects of ARC and the molecular pathways involved in the pathophysiology of schizophrenia." (PMID 35562887, 2022). "The transcriptomic and proteomic profiles of ARC-KO HEK293 cells presented here provide new evidence for the mechanisms underlying the effects of ARC and molecular pathways involved in schizophrenia pathophysiology." (PMID 35562887, 2022). "Arc/Arg3.1 (activity-regulated cytoskeletal-associated protein (ARC)) is a critical regulator of long-term synaptic plasticity and is involved in the pathophysiology of schizophrenia." (PMID 35562887, 2022). "Early growth response protein 1 (EGR-1) and activity-dependent cytoskeleton-associated protein (ARC) are two immediate early genes associated with schizophrenia." (PMID 36233357, 2022). "CYFIP1 was first associated with schizophrenia in studies that showed an enrichment of the ARC complex (containing 25 genes, of which CYFIP1 is one) in de novo CNV deletions from patients with schizophrenia." (PMID 34883502, 2020). "The inclusion of our new independent data in this analysis strengthened the evidence for association between RCVs in ARC and NMDARs and schizophrenia." (PMID 30420267, 2019). "When meta-analyzed with published case-control datasets, we found strong evidence that LoF variants in NMDAR complex genes were associated with schizophrenia (p = 1.6 × 10–4), but weaker evidence for association with ARC complex genes (p = .047)." (PMID 30420267, 2019). "In the EU group EGR3 SNP rs1877670 showed a trend toward association (p = 0.07), and the ARC SNP rs35900184 revealed a significant association with the schizophrenia diagnosis (p = 0.02)." (PMID 26474411, 2015). "Accordingly, variations in the immediate early gene EGR3, and its target ARC, should influence schizophrenia susceptibility." (PMID 26474411, 2015). "The ARC SNP rs35900184 maintained a significant association with the schizophrenia diagnosis (p = 0.0275) in the replication study." (PMID 26474411, 2015). "Recent high-profile studies of rare copy number variations (CNVs) and de novo variations enriched in schizophrenia patients have identified the importance of proteins that complex with ARC protein in the post-synaptic density in the risk for schizophrenia." (PMID 26474411, 2015). "Since no studies had been published investigating ARC SNPs for association with schizophrenia, selection of a single ARC SNP was made based only on high Δ MAF values in both race cohorts." (PMID 26474411, 2015). "To identify variations within the EGR3 and ARC loci that have a high likelihood for association with schizophrenia risk in two different racial groups, we used a two-step approach." (PMID 26474411, 2015). "And the ARC SNP rs35900184 displayed association with schizophrenia risk in both the EU and the AA populations (p = 0.0275 and p = 0.0448, respectively)." (PMID 26474411, 2015). "Thus, in a study on a large sample of patients, it was shown that both rare mutations and epigenetic regulation of ARC contribute to the pathogenesis of schizophrenia, at least in some patients." (PMID 37483450, 2023). "The behavioral changes were accompanied by increased early growth response protein 1 (EGR-1) and activity-dependent cytoskeleton-associated protein (ARC) levels in the sensorimotor cortex and hippocampus, regions implicated in circuitry dysfunction in schizophrenia." (PMID 36233357, 2022).
schizophrenia (continued). "This led us to hypothesize that other genes in this pathway that shared the characteristics of regulating memory and hippocampal LTD, such as the EGR3 target gene ARC, should also be candidates for a role in schizophrenia susceptibility." (PMID 29520222, 2018). "In addition, genes encoding proteins that bind to ARC, “ARC-complex proteins”, were identified in several large-scale, genome-wide schizophrenia genetic association studies." (PMID 29520222, 2018). "However, the ARC SNP, rs35900184, was significantly associated with schizophrenia in the combined group of EU, AA, and CH samples (p = 2.5X10-7), with a suggested odds ratio of 1.54 (95% confidence interval = 1.31–1.82)." (PMID 26474411, 2015). "We therefore carried out the current studies to test the hypothesis that EGR3 and ARC are schizophrenia risk associated genes." (PMID 26474411, 2015). "We therefore hypothesized that, like the preceding proteins in this putative pathway, which have each been implicated in schizophrenia risk, ARC should also be a schizophrenia susceptibility gene." (PMID 26474411, 2015). "Moreover, this is the first report associating an ARC SNP with schizophrenia and supports recent large-scale GWAS findings implicating the ARC complex in schizophrenia risk." (PMID 26474411, 2015). "In the current study we asked the whether genomic variations in the environmentally-activated IEGs EGR3 and ARC are associated with schizophrenia in two racial populations, EU and AA." (PMID 26474411, 2015). "Hence, ARC may be associated with schizophrenia symptoms, interact with other known schizophrenia genes, and demonstrate schizophrenia-related biological plausibility." (PMID 35562887, 2022). "Indeed, numerous genome wide association studies of copy number variations (CNVs), de novo mutations and SNPs, as well as our own resequencing study that identified a schizophrenia associated ARC SNP, have subsequently supported this hypothesis." (PMID 29520222, 2018). "Recently, a heritable chromosomal microdeletion that encompasses several genes, including ARC, was also shown to be associated with several neurodevelopmental psychiatric disorders such as attention deficit hyperactivity disorder and autism spectrum disorder in addition to schizophrenia." (PMID 29520222, 2018). "Previous sequencing studies have revealed the association between rare coding variants of ARC and NMDAR postsynaptic protein complexes and schizophrenia." (PMID 35562887, 2022). "In this context, it is noteworthy that several lines of evidence point towards a role of EGR-1 and ARC in schizophrenia, and that was why we decided to focus our studies on these two immediate early genes." (PMID 36233357, 2022). "In humans, ARC dysregulation contributes to various neurological and cognitive disorders, including schizophrenia, autism, fragile X syndrome, and Alzheimer’s disease." (PMID 35562887, 2022). "Combining the de novo enrichment results with the case-control meta-analysis results (LoF; frequency <0.1%), both ARC (p = 4.0 × 10–4) and NMDAR (p = 1.7 × 10–5) complexes were associated with schizophrenia." (PMID 30420267, 2019). "We provide further support for association between RCVs in ARC and NMDAR postsynaptic protein complexes and schizophrenia." (PMID 30420267, 2019). "These and other findings implicated ARC as a critical protein in a synaptic pathway involving voltage gated calcium channels, NMDARs, PSD95, FMRP, mGLuR and AMPARs, in schizophrenia risk." (PMID 29520222, 2018). "More recently, hypermethylation of eight CpG sites, and presence of several rare variants that reduce reporter gene activity, were reported in the putative ARC promoter region of schizophrenia patients vs. controls." (PMID 29520222, 2018). "Overall, substantial evidence suggests that ARC, an important regulator of synaptic function, memory, and LTD, influences risk for schizophrenia, and possibly other neuropsychiatric illnesses." (PMID 29520222, 2018).
schizophrenia (continued). "In the EU group of 386 schizophrenia cases and 150 controls EGR3 SNP rs1877670 and ARC SNP rs35900184 showed significant associations (p = 0.0078 and p = 0.0275, respectively)." (PMID 26474411, 2015). "Additionally, genetic disruption of ARC is known to recapitulate schizophrenia-relevant behavioral abnormalities." (PMID 35562887, 2022). "In summary, we present multiple lines of evidence that the “LDB2‐EGR” axis orchestrates the regulation of gene expression networks involving ARC and that a perturbation of this system is potentially related to the pathogenesis of mental disorders, such as schizophrenia and bipolar mania." (PMID 33656268, 2021). "While no individual gene was significantly associated with schizophrenia after genome-wide correction for multiple testing, we strengthen the evidence that rare exonic variants in the ARC (p = 4.0 × 10–4) and NMDAR (p = 1.7 × 10–5) synaptic complexes are risk factors for schizophrenia." (PMID 30420267, 2019). "In one of the largest sequencing studies of schizophrenia to date, we provide novel evidence that multiple voltage-gated sodium channels are involved in schizophrenia pathogenesis and confirm the involvement of ARC and NMDAR postsynaptic complexes." (PMID 30420267, 2019). "To test this hypothesis, we used next generation sequencing to resequence the ARC gene, and flanking regions, from schizophrenia patient and control subjects from two separate ethnic groups." (PMID 29520222, 2018). "No enrichment was observed for activity-regulated cytoskeleton-associated protein (P=0.23) or N-methyl-D-aspartate receptor (P=0.74) post-synaptic signalling gene sets previously implicated in schizophrenia." (PMID 26573769, 2016). "To test our hypothesis that ARC, a direct gene target of EGR3, is also a schizophrenia risk gene, we genotyped rs35900184 in a CH population of 491 cases and 491 controls in which EGR3 had previously demonstrated association with schizophrenia." (PMID 26474411, 2015). "Of the 134 CNS-related gene sets, we first evaluated those for which there existed prior, replicated evidence of enrichment for rare mutations in schizophrenia in at least three independent studies: the NMDAR protein network, ARC protein complex, and mRNA targets of FMRP." (PMID 26050040, 2015). "Previous studies have shown that schizophrenia patients have enriched de novo mutations in genes belonging to the postsynaptic density at glutamatergic synapses, such as components of the PSD complex, N-methyl-D-aspartic acid (NMDA) receptor signaling complex, ARC interactors, and the FMRP complex." (PMID 39604386, 2024). "Because ARC is a critical effector molecule and functions downstream of many signaling pathways, ARC dysfunction could be a nexus point for synaptic dysfunction in psychiatric diseases, especially schizophrenia." (PMID 35562887, 2022). "Indeed, ARC mRNA expression is decreased in the frontal cortex of schizophrenia patients." (PMID 29520222, 2018). "If so, then dysfunction of the gene activity-regulated cytoskeleton-associated protein (ARC), which is a downstream target of EGR3 and is similarly required for memory formation and hippocampal LTD in mice, may also confer risk for schizophrenia." (PMID 26474411, 2015). "However, to date there have been no reports of genetic association between SNPs in the ARC gene itself and schizophrenia." (PMID 26474411, 2015). "Thus, ARC may interact with HSP70 proteins, and the association of ARC with synaptic functions and neurodevelopmental processes may be related to the pathophysiology of schizophrenia." (PMID 35562887, 2022). "Since mice deficient for these proteins share phenotypes of LTD and memory deficits, similar to mice lacking Arc, we hypothesized that the ARC gene should likewise be a schizophrenia candidate gene." (PMID 29520222, 2018).
schizophrenia (continued). "Alternatively, it may be that lack of enrichment with the ARC protein for cognition implies that this system is specific for schizophrenia rather than for general cognitive ability." (PMID 24399044, 2014).
cardiac hypertrophy (13 papers, 2017 to 2024). "The upregulation of heart-related circRNA (HRCR) suppresses miR-223, overexpressing the gene for activity-regulated cytoskeleton-associated protein (ARC) and reducing the levels of cardiac hypertrophy induced by isoproterenol." (PMID 32455975, 2020). "Heart‐related circRNA (HRCR) can sponge miR‐223 and counteract the inhibition of ARC expression and activity by miR‐223, ultimately suppressing cardiac hypertrophy and heart failure." (PMID 37002786, 2023). "Wang and his colleagues found that circRNA HRCR acts as an endogenous sponge of miR-223 to regulate ARC expression in cardiac hypertrophy." (PMID 36003513, 2022). "HRCR can play the role of molecular sponge to “adsorb” mir-223, protect the heart through the mechanism of the HRCR/miR-223/ARC signaling pathway, and participate in the regulation of myocardial hypertrophy and heart failure." (PMID 36033554, 2022). "HRCR decreases the level of ARC expression and enhances myocardial hypertrophy produced by isoproterenol (ISO) via sponging with downregulated MiR-223." (PMID 34977015, 2021). "Increases the expression of activity-regulated cytoskeleton-associated protein (ARC; an apoptosis repressor with a CARD domain), and inhibits heart failure and cardiac hypertrophy." (PMID 32300345, 2020). "Modulation of circHRCR/miR-223/ARC levels provides an attractive therapeutic target for the treatment of cardiac hypertrophy and heart failure." (PMID 32148552, 2020). "CircRNA HRCR can sequester and inhibit miR-223 activity and was then used in the treatment of cardiac hypertrophy and heart failure through increasing the ARC expression." (PMID 32148552, 2020). "The heart-related circRNA HRCR is known to prevent cardiac hypertrophy and heart failure by sponging miR-223, which suppresses ARC expression." (PMID 30670716, 2019). "In general, HRCR can adsorb the endogenous miR-223, then inhibit its function and up-regulate the expression of its downstream target ARC, thus playing a role in inhibiting pathological cardiac hypertrophy." (PMID 28287427, 2017). "This is a new signal pathway, which is composed of HRCR/miR-223/ARC, participating in the regulation of cardiac hypertrophy and heart failure." (PMID 28287427, 2017). "Further investigation demonstrated that circHRCR could repress abnormal cardiac hypertrophy and heart failure through the circHRCR/miR-223/ARC axis." (PMID 30112184, 2018). "They further found that the overexpression of miR‐223 led to cardiac hypertrophy, and HRCR increased the expression of the antiapoptotic protein ARC, an inhibitor of apoptosis, by sequestering miR‐223, thereby reducing the cardiac hypertrophy response." (PMID 39239069, 2024).